MAP1S (microtubule associated protein 1S)
Description:
Microtubule-associated protein that mediates aggregation of mitochondria resulting in cell death and genomic destruction (MAGD). Plays a role in anchoring the microtubule organizing center to the centrosomes. Binds to DNA. Plays a role in apoptosis. Involved in the formation of microtubule bundles (By similarity).
Synonyms: VCY2IP-1; BPY2IP1; C19orf5; MAP8; VCY2IP1; FLJ10669
Tractability: PROTAC: ubiquitination databases record sites on it; its protein half-life has been measured.
Gene: Protein-coding gene on chromosome 19 (17,718,607 to 17,734,518, forward strand). Ensembl gene ENSG00000130479.
Subcellular location: Nucleus; Cytoplasm, cytosol; Cytoplasm, cytoskeleton; Cytoplasm, cytoskeleton, spindle
Subcellular location (Human Protein Atlas): Cytosol; Principal piece; Nucleoli; Nucleoplasm
Gene Ontology:
Molecular function: actin filament binding; beta-tubulin binding; DNA binding; DNA nuclease activity; microtubule binding; protein binding; tubulin binding; WD40-repeat domain binding; actin binding; identical protein binding
Biological process: metaphase chromosome alignment; microtubule anchoring at centrosome; microtubule bundle formation; mitotic spindle organization; neuron projection morphogenesis; autophagy; axonogenesis; brain development; dendrite development; microtubule cytoskeleton organization; mitochondrion transport along microtubule; nervous system development; regulation of microtubule depolymerization
Cellular component: cell projection; centrosome; cytosol; microtubule; microtubule organizing center; mitotic spindle microtubule; nucleolus; nucleoplasm; nucleus; perinuclear region of cytoplasm; spindle; synapse; dendrite; microtubule associated complex; neuronal cell body; cytoskeleton; microtubule cytoskeleton
Genetic constraint (gnomAD): Loss-of-function variants: 27 observed, 47.93 expected, observed/expected ratio (o/e) 0.56, 90% interval 0.41 to 0.78. The synonymous counts are far from expectation, so gnomAD's model fits this gene poorly and the ratio says little. Missense variants: 1,607 observed, 1,362.9 expected, observed/expected ratio (o/e) 1.18, 90% interval 1.13 to 1.23. Synonymous variants: 826 observed, 634.01 expected, observed/expected ratio (o/e) 1.3, 90% interval 1.23 to 1.38.
Homologues: Orthologues: chimpanzee MAP1S (99% identical), macaque MAP1S (94% identical), pig MAP1S (83% identical), dog MAP1S (83% identical), guinea pig MAP1S (65% identical), rat Map1s (65% identical), mouse Map1s (64% identical), zebrafish map1sa (45% identical), tropical clawed frog MAP1S (43% identical), zebrafish map1sb (41% identical). Paralogues in human: MAP1B (42% identical), MAP1A (30% identical).
Diseases named in the same sentence as MAP1S in open-access papers:
MAP1S is named in the same sentence as 31 diseases in open-access papers, as found by Europe PMC text mining. Sharing a sentence is not in itself a finding about the gene and the disease. The quoted sentences say what the papers report.
liver fibrosis (7 papers, 2016 to 2025). "Studies have also revealed that oral supplementation with spermidine can reduce liver fibrosis and hepatocellular carcinoma by stabilizing the microtubule‐associated protein, MAP1S, to increase autophagy signaling." (PMID 40760821, 2025). "Spermidine, a non-canonical Nrf2 inducer, increased MAP1S stability and promoted autophagy flux through depletion of cytosolic HDAC4, which in turn reduced liver fibrosis and extended lifespan in MAP1S-deficient mice." (PMID 32724454, 2020). "Spermidine was shown to prevent liver fibrosis and HCC by activating microtubule-associated protein 1S (MAP1S)-mediated autophagy." (PMID 41440201, 2025). "These observed anti-fibrotic impacts of MAP1S rely upon the promotion of autophagy flux, once again, showing the importance of increased autophagy flux in the development of liver fibrosis." (PMID 32724454, 2020). "Consistently, spermidine suppressed liver fibrosis by activating Nrf2 and increasing MAP1S-mediated autophagy, which was partly reversed in Nrf2 or p62 single KO mice and completely inhibited in Nrf2 and p62 DKO mice." (PMID 32724454, 2020). "In contrast, SPD was proposed to prolong life span and prevent liver fibrosis by inhibiting the deacetylation of MAP1S to enhance autophagy flux." (PMID 31907336, 2020). "Further overexpression of LC3 in MAP1S−/− mice induced higher stress of fibronectin deposition and led to obvious liver fibrosis." (PMID 26750654, 2016). "We have shown that MAP1S facilitates the turnover of fibronectin through lysosomes in liver tissues and suppresses liver fibrosis in mouse models." (PMID 27236336, 2016). "Because of the involvement of MAP1S in both liver fibrosis and ccRCC, we were triggered to investigate the roles of MAP1S in renal fibrosis." (PMID 27236336, 2016). "We have already reported that MAP1S knockout mice develop liver fibrosis and sinusoidal dilation in liver tissues when mice are under the stress of excessive production of fibronectin induced by LC3." (PMID 27236336, 2016). "Notably, in LC3-overexpressing MAP1S KO mice, overexpression of LC3 enhanced the synthesis of fibronectin and MAP1S depletion caused the impairment of autophagy flux, synergistically resulting in fibronectin accumulation and aggravated liver fibrosis." (PMID 32724454, 2020).
clear cell renal cell carcinomas (5 papers, 2016 to 2022). "Microtubule-associated protein 1S (MAP1S)-mediated lipophagy promotes lipid droplet clearance and higher levels of MAP1S have been associated with reduced tumour growth and metastasis and an increased patient survival in clear-cell renal cell carcinoma." (PMID 30081476, 2018). "Previously, we reported that MAP1S suppresses hepatocellular carcinogenesis in a mouse model and predicts a better prognosis in patients suffering from clear cell renal cell carcinomas." (PMID 27236336, 2016). "Microtubule-associated protein 1S (MAP1S)-mediated lipophagy promotes the elimination of lipid droplets, and high expression of MAP1S is associated with the suppression of tumor growth and metastasis and an improved prognosis in clear-cell renal cell carcinoma." (PMID 33530546, 2021). "A search against COSMIC identified a number of mutations found in tumors (i.e. adenocarcinoma, squamous cell carcinoma, malignant melanoma and clear cell renal cell carcinoma) localizing within fragments corresponding to SPATA22, ZBTB17, CCT7, MAP1S and PDIA3 proteins." (PMID 35205757, 2022).
hepatocellular carcinoma (5 papers, 2015 to 2025). A malignant tumor that arises from hepatocytes. "A deficiency of MAP1S causes defects in autophagy and enhances the initiation and development of hepatocellular carcinomas." (PMID 26701856, 2016). "MAP1S-deficient mice developed more malignant hepatocellular carcinomas." (PMID 26701856, 2016). "In a mouse model of chemical carcinogen-induced hepatocellular carcinomas, we found that the autophagy-defective MAP1S-deficient mice exhibit higher levels of genome instability and develop more tumor foci and higher malignance of hepatocellular carcinomas than the wild-type mice." (PMID 26571030, 2015). "The polyamine spermidine can improve MAP1s instability induced by HDAC4 and inhibit the occurrence of cirrhosis and hepatocellular carcinoma by promoting autophagy." (PMID 35637410, 2022). "The tumor suppressive function of autophagy regulator MAP1S and its interactive protein LRPPRC has been documented in multiple types of cancers including human ovarian cancer, prostate cancer, gastric cancer and carcinogen-induced mouse hepatocellular carcinomas." (PMID 26571030, 2015).
prostate carcinoma (4 papers, 2015 to 2022). A carcinoma that arises from epithelial cells of the prostate gland. "High levels of MAP1S are associated with low malignancies of prostate cancer and predict a better survival of prostate cancer patients." (PMID 26701856, 2016). "Further examination noted prostate cancer patients with high level of MAP1S demonstrate better prognosis compared to those with low level of MAP1S." (PMID 35317831, 2022). "It is possibly the reason that prostate cancer patients with lower levels of MAP1S in their tumor tissues had a shorter time of survival than the patients with high levels of MAP1S." (PMID 26750654, 2016). "The MAP1S-mediated autophagy suppresses tumorigenesis as suggested in a mouse liver cancer model and in prostate cancer patients." (PMID 26571030, 2015).
renal fibrosis (4 papers, 2016 to 2022). A final common manifestation of a wide variety of chronic kidney diseases characterized by glomerulosclerosis and tubulointerstitial fibrosis. "MAP1S deficiency in mice contributed to the accumulation of fibronectin and further aggravated the progression of renal fibrosis in aged mice." (PMID 36081940, 2022). "MAP1S deficiency led to accumulation of fibronectin and development of renal fibrosis in both mice and human beings." (PMID 27236336, 2016). "Combining the data from culture cells and mouse models, we conclude that MAP1S-mediated autophagy facilitates the degradation of fibronectin and MAP1S deficiency causes renal fibrosis in patients." (PMID 27236336, 2016). "MAP1S depletion eventually causes renal fibrosis in aged mice." (PMID 27236336, 2016). "Therefore, high levels of fibronectin are associated with low levels of MAP1S in patients suffering from renal fibrosis." (PMID 27236336, 2016). "Therefore, MAP1S depletion causes renal fibrosis in aged mice." (PMID 27236336, 2016). "Therefore, MAP1S deficiency may cause the accumulation of fibronectin and the development of renal fibrosis." (PMID 27236336, 2016). "Of note, another study showed that microtubule-associated protein 1S (MAP1S), as an autophagy activator, interacted with LC3 and involved in renal fibrosis." (PMID 36081940, 2022). "As expected, the depletion of MAP1S disrupted autophagy-dependent clearance of fibronectin and induced fibronectin accumulation during renal fibrosis." (PMID 32724454, 2020). "Similar to the findings in the liver, a recent study further identified that MAP1S-related autophagy is involved in the regulation of renal fibrosis." (PMID 32724454, 2020). "The suggested renal fibrosis in aged MAP1S−/− mice by the fibronectin staining was further confirmed by immunoblot analyses of the levels of fibrosis-related proteins TGF-β and α-SMA and Sirius Red staining." (PMID 27236336, 2016). "Similar approaches to restore MAP1S-mediated autophagy flux in patients to reverse renal fibrosis should be feasible and promising." (PMID 27236336, 2016). "Depletion of MAP1S in mice leads to an accumulation of fibrosis-related proteins and the development of renal fibrosis in aged mice." (PMID 27236336, 2016). "To further understand the mechanism by which MAP1S affects renal fibrosis, we tested the impact of MAP1S on the levels of pyroptosis." (PMID 27236336, 2016). "Therefore, MAP1S-mediated autophagy helps renal tissues to maintain low levels of fibronectin and suppress the development of renal fibrosis." (PMID 27236336, 2016). "Therefore, MAP1S promotes autophagy and suppresses renal fibrosis." (PMID 27236336, 2016). "In addition, the inhibition of MAP1S in near-end renal tubular cells may lead to the development or progression of pyroptosis, which is further suggestive of the close relationship between pyroptosis and renal fibrosis." (PMID 34007404, 2021). "Although no renal fibrosis was observed in such young mice, levels of fibrosis-related proteins TGF-β and α-SMA were increased due to MAP1S depletion." (PMID 27236336, 2016).
breast carcinoma (3 papers, 2014 to 2024). "The antitumor mechanisms of hTLR5 signaling in breast cancer cells suggest MAP1S as an important autophagic adapter, which is associated with tumor suppression via autophagy regulation." (PMID 36539522, 2022). "In this study, we further investigated the underlying antitumor mechanisms of TLR5 signaling in breast cancer cells by examining the function of MAP1S." (PMID 24466264, 2014). "Remarkably, MAP1S was associated with inhibition of cell proliferation and migration of flagellin-treated breast cancer cells." (PMID 24466264, 2014). "Collectively, these results indicated that MAP1S is associated with breast cancer TLR5 pathway." (PMID 24466264, 2014). "Additionally, TLR5 agonist flagellin has been found to inhibit the cell state of activation and induce autophagy, and the autophagy protein MAP1S (Microtubule Associated Protein 1S) has been shown to regulate the flagellin/TLR5 signaling pathway in breast cancer cells." (PMID 38903515, 2024). "In this study, we showed that MAP1S acted as a critical regulator in the antitumor activity of TLR5 signaling in breast cancer cells." (PMID 24466264, 2014). "We observed that MAP1S levels were up-regulated in response to flagellin treatment in human breast carcinomas and MAP1S regulated cytokine expression induced by TLR5 signaling." (PMID 24466264, 2014). "Taken together, these observations indicate that MAP1S is an autophagic regulator involved in TLR5 signaling in breast cancer cells." (PMID 24466264, 2014). "In the early stage of TLR5 activation, MAP1S modulated the production of proinflammatory cytokines and unknown soluble factors to elicit potent antitumor activity in breast carcinomas." (PMID 24466264, 2014). "In this study, we focus on the role of MAP1S in TLR5-induced suppression of breast cancer." (PMID 24466264, 2014). "Therefore, in addition to autophagy, G1 arrest induced by flagellin treatment is another reason for MAP1S-involved inhibition of breast cancer cell proliferation." (PMID 24466264, 2014). "In this study, we found TLR5 agonist flagellin inhibited the cell state of activation and induced autophagy, and reported that autophagy protein MAP1S regulated the flagellin/TLR5 signaling pathway in breast cancer cells through enhancement of NF-κB activity and cytokine secretion." (PMID 24466264, 2014). "In the breast cancer, TLR5 activation leads to autophagy via the MAP1S autophagy protein which induces IL-8 and TNF-α in the MCF-7 cell line." (PMID 36539522, 2022). "We found that MAP1S is ubiquitously expressed in the breast epithelial cell line MCF-10a and breast cancer cell lines including MCF-7, MDA-MB-435s, MDA-MB-468, T47D, MDA-MB-231 and MDA-MB-431." (PMID 24466264, 2014). "In agreement with this study, we observed that elevated MAP1S levels were accompanied by degradation of MyD88 and attenuation of MyD88-dependent transcription factor activation, suggesting that MAP1S provides negative feedback regulation in the TLR5 signaling pathway of breast cancer cells." (PMID 24466264, 2014).
Huntington disease (2 papers, 2015 to 2016). Huntington disease (HD) is a rare neurodegenerative disorder of the central nervous system characterized by unwanted choreatic movements, behavioral and psychiatric disturbances and dementia. "In this study, we implicated and established a mechanism for the role of MAP1S in the development of Huntington's disease through its role in multiple steps of autophagy." (PMID 26540094, 2015). "HDAC4 inhibition has demonstrated significant effects to increase the stability of MAP1S, MAP1S-mediated autophagy flux and degradation of mutant Huntingtin aggregates that are directly impact Huntington's disease." (PMID 27236336, 2016). "This reveals a new potential to treat Huntington's disease by interrupting the specific interaction between HDAC4 and MAP1S." (PMID 26540094, 2015).
malignant melanoma (2 papers, 2012 to 2022). "Although not discussed in great detail here, RASSF1A can also promote cell death utilizing the autophagic protein, C19ORF5/MAP1S, the Hippo pathway components MST1/2 and possibly Salvador, and, in melanoma cells, influence Bcl-2 levels and activate apoptosis signal regulating kinase 1 (ASK-1)." (PMID 22701175, 2012).
ovarian carcinoma (2 papers, 2014 to 2015). A malignant neoplasm originating from the surface ovarian epithelium. "Based on a huge data set from The Cancer Genome Atlas, somatic mutations in MAP1S were found to be significantly associated with poor prognosis of patients suffering from ovarian cancer." (PMID 26571030, 2015). "Dysfunction of LRPPRC and MAP1S is associated with poor survival of ovarian cancer patients." (PMID 24722279, 2014). "Based on the somatic mutation data of 17301 genes from 316 ovarian cancer patients from The Cancer Genome Atlas, mutations in both LRPPRC and MAP1S were found to reduce the survival of patients." (PMID 24722279, 2014).
Parkinson disease (2 papers, 2019 to 2023). A progressive degenerative disorder of the central nervous system characterized by loss of dopamine producing neurons in the substantia nigra and the presence of Lewy bodies in the substantia nigra and locus coeruleus. "There are 147 SNPs associated with the MAP1S gene and Parkinson’s disease through meta-analyses." (PMID 37510383, 2023). "MAP1S has been reported to interact with mitochondrion‐associated leucine‐rich PPR‐motif containing protein that interacts with the mitophagy initiator and Parkinson disease‐related protein Parkin." (PMID 31495056, 2019).
clear cell carcinoma (1 paper, 2022). "Compared with that in clear cell carcinoma, the level of MAP1S in normal renal cells is higher, and a high level of MAP1S is associated with a lower malignant degree and metastasis probability and better prognosis." (PMID 35136038, 2022).
Crohn disease (1 paper, 2020). A gastrointestinal disorder characterized by chronic inflammation involving all layers of the intestinal wall, noncaseating granulomas affecting the intestinal wall and regional lymph nodes, and transmural fibrosis. "An autophagy-related protein, microtubule-associated protein 1S (MAP1S), interacts with LC3B, and is involved in autophagosomal formation, which enhances the survival of intestinal epithelial cells via Wnt/β-catenin signalling in Crohn’s disease." (PMID 32384691, 2020).
pancreatic cancer (1 paper, 2015). "To understand whether the elevation in TGFβ levels and elevation in levels of MAP1S and autophagy markers are coincident or have any cause-effect relationship, we treated two pancreatic cancer cell lines with TGFβ to test its impact on the levels of MAP1S and autophagy markers." (PMID 26571030, 2015). "We reason that in response to metabolic stress triggered by development of pancreatic cancer, MAP1S-mediated autophagy flux is activated to suppress genome instability and tumorigenesis." (PMID 26571030, 2015). "Here, we further show that MAP1S-mediated autophagy is activated in pancreatic cancer patients." (PMID 26571030, 2015). "In the present study, we showed that levels of TGFβ, MAP1S and LC3 proteins were dramatically elevated in pancreatic cancer tissues, and TGFβ enhances autophagy flux through MAP1S to suppress the development of pancreatic ductal adenocarcinomas." (PMID 26571030, 2015). "Real-time PCR analyses revealed that TGFβ had no significant impact on the expression of MAP1S gene in pancreatic cancer cell line PANC-1 and Capan-2." (PMID 26571030, 2015). "The elevation in the intensities of MAP1S and autophagy markers in human pancreatic cancer was confirmed by immunoblot analysis of the same sets of normal and tumor tissue samples." (PMID 26571030, 2015).
pancreatic ductal adenocarcinoma (1 paper, 2015). An infiltrating adenocarcinoma that arises from the epithelial cells of the pancreas. "We collected the tumor and its adjacent normal tissues from 33 randomly selected patients of pancreatic ductal adenocarcinomas to test the association between TGFβ and autophagy markers MAP1S and LC3." (PMID 26571030, 2015). "In this study, we try to understand the relationship between TGFβ and MAP1S-mediated autophagy in pancreatic ductal adenocarcinoma." (PMID 26571030, 2015). "TGFβ may suppress the development of pancreatic ductal adenocarcinomas by enhancing MAP1S-mediated autophagy." (PMID 26571030, 2015). "Here we show that levels of TGFβ and autophagy markers MAP1S and LC3 are dramatically elevated in tumor tissues from patients with pancreatic ductal adenocarcinomas." (PMID 26571030, 2015).